CD4 (CD4 molecule)
Diseases named in the same sentence as CD4 in open-access papers (continued):
Sharing a sentence is not in itself a finding about the gene and the disease.
tumor (continued). "In vivo antitumor experiments demonstrated that upregulationof mitochondrial OXPHOS pathways not only promoted the tumor infiltrationof CD8+/CD4+ T lymphocytes and IFN-γ secretionbut also suppressed Treg cells and MDSCs." (PMID 37901179, 2023). "According to the results of our single-cell transcriptomic analysis and flow cytometry of tumor-infiltrating immune cells, OV-mOX40L treatment decreased Foxp3+ Tregs, activated CD4+ and CD8+ T cells, and resulted in less exhausted CTLs." (PMID 37554264, 2023). "We first observed a decreased abundance of CD4 + CD8- (CD4+ positive) cells in all tumor groups prior to the proton therapy treatment." (PMID 38092866, 2023). "Increased Treg numbers and Treg/CD8+ T cells ratios and lower IFNγ-producing CD4+ T cell numbers indicated an immunosuppressive tumor environment in cSCC from SOTRs." (PMID 37887285, 2023). "Together, these data suggest that tumor CD103+ CD8 T cell formation is CD40L-dependent but CD4 independent." (PMID 37072485, 2023). "The data presented here is descriptive and suggestive of the tumor immunity mechanism focused on CD4+ CTLs." (PMID 38077321, 2023). "The tumor environment contains various immune cells, such as CD4+ and CD8+ T cells, natural killer cells, regulatory T cells (Tregs), and myeloid-derived suppressor cells (MDSCs)." (PMID 37894457, 2023). "Macrophages, neutrophils, and mast cells mostly exhibit pro-tumor qualities, while high numbers of T cells (specifically CD4+ or CD8+ T cells) or B cells predicted worse capsular and perineural invasion." (PMID 36770929, 2023). "Given the critical role of CD4 T cells in tumor control and their potential tumor-killing capacity, we further characterized these cells using a panel of lineage and functional markers." (PMID 37185301, 2023). "Cancer cells can inhibit the functions of T lymphocytes, such as that of CD8 and CD4, which play a crucial role in recognizing and eliminating cancer cells, thereby creating a challenge in anti-tumor immune responses." (PMID 38164436, 2023). "This drug was demonstrated to effectively deplete the Aire+ cells in lymphoid organs, rescuing tumour antigen‐reactive thymic CD4+ T cells in melanoma models." (PMID 37403792, 2023). "The high frequency of antigen-specific CD4+ T cells after DIVA2 reveals DIVA2 as a promising tumor vaccination tool." (PMID 37727790, 2023). "Most cancer vaccines rely on dendritic cells to activate tumor antigen-specific CD4+ and CD8+ T cells, as well as antibody-producing B cells capable of long-lasting antitumor responses through the generation of immunological memory." (PMID 36839766, 2023). "FoxP3+CD4+ regulatory T cells (Tregs) suppress immune responses and their removal enhanced anti-tumor immunity, resulting in tumor regression in mice; therefore, Treg control has become a new target in cancer immunotherapy." (PMID 37729184, 2023). "For instance, the alkylating agent temozolomide reduced the intratumor Tregs/CD4+ ratios in tumor-bearing mouse models, whereas gemcitabine limited Tregs accumulation in mice affected by pancreatic adenocarcinoma." (PMID 37173937, 2023). "It has been shown that a significant proportion of cases formerly classified as lymphoepitheloid PTCL, NOS (so-called Lennert lymphoma) represent CD4+ neoplasms characterized by a TFH phenotype and are best classified as TFHL." (PMID 37500795, 2023). "In our work, we showed that CD4+ effector T cells are also able to independently eradicate established tumours as efficiently as CD8+ cytolytic T cells." (PMID 37316667, 2023). "Once bound to MHC II, the cytoplasmic domains of LAG-3 propagate inhibitory signals in CD4+ T lymphocytes, leading to its inactivation and the escape of tumor cells from undergoing immune cell-mediated apoptosis." (PMID 37345111, 2023). "The intricate TME comprises not only tumor cells but also diverse types of immune cells, including CD4+ FOXP3+ Tregs, myeloid‐derived suppressor cells (MDSCs) and tumor‐associated macrophages (TAMs)." (PMID 37818745, 2023).
tumor (continued). "The high frequency T-cell clonotypes were higher than the highest control value for 100% of CD8 T-cells and 80% of CD4 T-cells showing that an effective anti-tumor response was identifiable in all animals." (PMID 37033929, 2023). "While CD8+ T-cells are important in the direct killing of tumor cells, helper T-cells (CD4+ T-cells) support the role of CD8+ T-cells." (PMID 38201559, 2023). "For example, oral administration of hLF increased the numbers of tumor-infiltrating CD4+ and CD8+ T cells in a mouse model of head and neck squamous cell carcinoma." (PMID 37111542, 2023). "It is important to note that TSLP secreted by the tumor activates myeloid DCs; however, in the skin, specifically in keratinocytes, TSLP exhibits CD4+ T cell-mediated anti-tumor activity." (PMID 37175480, 2023). "Histological and immunohistochemical analyses showed increases in CD8+ and CD4+ tumour-infiltrating lymphocytes (TILs) in most paired tumours after CAN-3110 treatment." (PMID 37853118, 2023). "Among the tumor-infiltrating T lymphocytes (TILs), apart from CD8+ T cells, it is also known that CD4+ T cells play important roles in anti-tumor immunity, e.g., the activation and growth of cytotoxic CD8+ T cells." (PMID 36049666, 2023). "RT combined with HT can also increase the activity of immune cells, such as CD8+ T cells, CD4+ T cells, dendritic cells, and NK cells, resulting in tumor death." (PMID 37107299, 2023). "Tumour-infiltrating lymphocytes (TILs) encompass CD4+ T-cells, CD8+ T-cells, and NK T-cells, which infiltrate the tumour site from the bloodstream." (PMID 38136392, 2023). "In ovarian cancer (OC), tumor-infiltrating T cells encompass several distinct types, each characterized by specific surface markers, including CD4+, CD8+, proliferative, and unconventional T cells." (PMID 38132318, 2023). "For example, infiltration of CD4+ TRM increased the anti-tumor activity of tissues by promoting the recruitment of immune cells and was associated with a good prognosis of tumors." (PMID 37483596, 2023). "By identifying the antigens made by HLA class II molecules in the tumor microenvironment, CD4 T cells can encourage antitumor responses." (PMID 36891324, 2023). "In the tumor-draining lymph node, CTls, such as CD4+ helper T cells, need three signals from the APC to become activated and polarized into an effector cell." (PMID 37511431, 2023). "In CRC, STM2457 combined with PD-1 antibody demonstrates a synergistic effect, characterized by enhanced suppression of tumor volume and increased CD4+ or CD8+ T cells infiltration." (PMID 37015927, 2023). "CD4+ T cells also induce humoral responses to tumor antigens on B cells through the interaction of CD40 with CD40 ligands." (PMID 37033978, 2023). "While the tumor cells in our previous study of EBV+ PTCL were of the CD4+CD8-CD56- phenotype, we found that various proportions of EBER+ cells were of the null type (CD45RO-CD3-CD4-, also CD20-)." (PMID 36851637, 2023). "CpG-Tag-NP immunization led to increased accumulation of CD8+ and CD4+ T cells expressing the activation marker CD69 in BALF when immunized mice were challenged with 4T1 tumor cells via tail vein injection." (PMID 36839766, 2023). "Hypoxia, often due to chaotic and insufficient tumour microcirculation, has detrimental effects on effector functions of both CD4+ and CD8+ T lymphocytes and supports the proliferation and migration of immunosuppressive cells." (PMID 36564565, 2023). "Tumors present with CD8 and CD4 T lymphocytes in the tumor core and edge, which is crucial for the efficacy of immunotherapies." (PMID 37296466, 2023). "TILs can vary in distribution and density in the tumor, relative mix of the distinct cell types (e.g., CD4+ T cells, CD8+ T cells, Treg; proinflammatory macrophages vs regulatory macrophages) and activation states." (PMID 36816748, 2023).
tumor (continued). "Nevertheless, tumour progression was accompanied by increased infiltration of activated effector memory CD4+ T cells and TH1 (FoxP3-T-bet+) and TREG (FoxP3+T-bet-) subsets were present in established tumours." (PMID 37153625, 2023). "Th2 cells, Th1 cells, and Treg are all categorized as CD4 + T helper cells, and they play an integral role in the tumor immune response." (PMID 37345110, 2023). "CCL2 is secreted by different cell types, like T cells, monocytes, and also tumor cells, and works as a chemoattractant for myeloid cells, activated CD4+ and CD8+ T cells, and NK cells." (PMID 37284199, 2023). "Previous research has shown that Th2-polarized CD4+ T cells secrete cytokines such as IL-4, -5, -6 and -10, which reduce T cell antitumor activity and increase macrophage pro-tumor activity." (PMID 37225919, 2023). "One intriguing observation of our study was that CD4-mediated tumor control resulted in potent memory responses that protected mice from tumor rechallenge." (PMID 37185301, 2023). "Th17 cells can stimulate CD8 + CTL response through IL-2 and pMHC I, and stimulate the expression of CCL2 and CCL20 in tumor microenvironment to promote the recruitment of various inflammatory leukocytes (DCs, CD4 + and CD8+ T cells)." (PMID 36874093, 2023). "While inducing CTL differentiation, some CD4+ Th1 cells also have the ability to kill tumor cells directly." (PMID 36872320, 2023). "Most immunotherapies focus on eliciting an anti-tumor T cell response that requires a collaboration of at least CD4 T Helper cells and CD8 cytotoxic T cells (CTLs)." (PMID 38239396, 2023). "We found that high levels of CD4+ T cells distributed in the 0–10-μm distance to tumor cells at baseline predicted poor survival." (PMID 37275884, 2023). "Higher CD4+ T cells in the tumor compartment and a shorter nearest distance of T-cell subsets at baseline predicted poor OS." (PMID 37275884, 2023). "In accordance with previous studies, the adoptive treatment with MHC‐II‐restricted and MAGE‐A3‐specific CAR‐T cells is efficacious to generate tumor eradication, which highlights the importance of CD4+ T cells in ACT therapy." (PMID 37829505, 2023). "In conclusion, low-risk TME is tend to be one with ‘hot’ tumor features such as CD8 T cells and activated CD4 Tm, while high-risk TME is more likely to be one with suppressive myeloid cells infiltration pattern such as M0 and neutrophils." (PMID 37183243, 2023). "Tumors with loss of or mutated LKB1 had significantly lower infiltration of immune-competent cells (CD4, CD8-effector, and NK cells), tumor-associated macrophages (TAMs), and T regulatory cells than tumors harboring WT LKB1." (PMID 36871040, 2023). "Compared to the invasive border at the periphery of the tumor at the resected vein or venous surface, a greater percentage of CD4 cells are regulatory T cells in the central tumor." (PMID 37587309, 2023). "Through the expression of T cell receptor (TCR) α/β, CD4+ or CD8+ T cells recognize tumor antigens and autoantigens and act on specific cancer cells, thereby exerting anti-tumor immunity." (PMID 37978469, 2023). "Consistent with our previous findings, Emut Vax significantly increased tumor infiltrating CD4+ T cells." (PMID 36875137, 2023). "CD4+ helper T cells provide help signals to other immune cells, and antibodies produced against the TAAs can directly bind to tumor cells, facilitating their destruction." (PMID 37681891, 2023). "To examine the ability of CD4 T cells to directly kill tumor cells, we co-cultured splenic CD4 T cells from mice that rejected tumors with HT-29 tumor cells ex vivo and evaluated tumor cell survival." (PMID 37185301, 2023). "Since tumor-derived gp96 confers its antitumor immune responses by priming effector CD4+ and CD8+ T cells, we demonstrated that this can be augmented with ICB." (PMID 37427594, 2023). "So far, the indicated studies generated exciting data about the therapeutic potential and presence of CD4+ CTL in tumor infiltrates." (PMID 37965314, 2023).
tumor (continued). "This promising divalent therapy Nanovaccine_siTGF‐β1 + Pexidartinib boosted T‐cell infiltration into tumors, resulting in the highest levels of tumor‐infiltrating CD4+ T cells, and CD8+ T cells (p < 0.0001)." (PMID 37434063, 2023). "A large accumulation of CD4+ T cells both within and surrounding the tumor site in GCT02‐treated mice was observed." (PMID 36890859, 2023). "Emut Vax treatment significantly increased proportions of anti-tumor CD4+ Th1, Th9 and Th17 cells in the lung tumors, while the vaccine decreased the abundance of Treg cells." (PMID 36875137, 2023). "Along with the impaired antitumor immunity, increased levels of PD‐1 were detected in tumor‐infiltrating CD4+ and CD8+ T cells from Cbx4 knockout mice." (PMID 37691307, 2023). "High baseline tumor PD-L1 expression (≥1%), low PD-1+CD8+ cell density in tumors and a low ratio of PD-L1+/CD4+ T cells were identified as being associated with better OS." (PMID 37833255, 2023). "High numbers of CD4+ TH1 in the tumor microenvironment are also correlated with a favorable prognosis." (PMID 37009375, 2023). "In the context of CCA, the overall quantity of tumor-infiltrating Tregs and CD4+ CTLs serves as independent prognostic markers for tumor grading and the Union for International Cancer Control (UICC) stage." (PMID 38213535, 2023). "As for infiltrating cells, oxaliplatin upregulated the expression of CD134 and downregulated TIM-3 of CD4+ T cells, downregulated the PD-L1 expression of DC cells, which contributed to improve the anti-tumor effect and the treatment response of ICIs." (PMID 36960067, 2023). "Following tumor insult, both the CD4+ and CD8+ populations had significantly contracted in the naive mice." (PMID 37345658, 2023). "Our study provides a model with human T cells and human tumor cells to further investigate the anti-tumor activity of CD4 CTLs." (PMID 37185301, 2023). "We analyzed six tumor-infiltrating immune cells, including B cells, CD4 T cells, CD8 T cells, dendritic cells, macrophages and neutrophils." (PMID 36864364, 2023). "TIMER database was used to analyze tumor infiltrating immune cells (including B-cell, CD4+T-cell, CD8+T-cell, macrophages, neutrophils and myeloid dendritic cells)." (PMID 36711038, 2023). "The natural killer (NK) cells, macrophages, T helper 1 (Th1) cells, and Th17 cells, differentiated from CD4+ T cells, positively promote tumor immunity." (PMID 37397393, 2023). "The primary objective of this study is to identify and compare the spatial distribution of CD3+/CD4+ and CD3+/CD8+ TILs and tumour-associated macrophages (TAMs) in OE and EAOC." (PMID 37569458, 2023). "By fluorescent microscopy, we observed that the onset of tumor cytolysis was more rapid in CD8+ T cells than in CD4+ T cells." (PMID 36915911, 2023). "In tumor-dLN, there was an increased frequency of resident CD4+ T cells and enhanced IFNγ and IFNγ+ TNF producing CD8+ and CD4+ T cells in mice with macrophage-specific PP2AcKO." (PMID 36757811, 2023). "Inhibiting CD39, an ecto-enzyme converting extracellular ATP to AMP, through antibody activates NLRP3 inflammasomes leading to IL-18 secreting that expands intra-tumor effector CD4+ and CD8+ T cells." (PMID 36932407, 2023). "Analysis of 624 patients with squamous cell lung cancer from the TCGA and GEO data sets identified an immune exhausted subclass of tumours, classified by an upregulation of inhibitory checkpoints, M2 macrophages and CD4+ regulatory T cells." (PMID 37143952, 2023). "TIL subpopulations have different locations and can influence the prognosis in different ways, such as the CD8-positive one at the core of the tumor and the CD4-positive one at the vicinity of the tumor bulk." (PMID 37958547, 2023). "For example, the expression level of SERPINE2 was positively correlated with the level of CD4 T cells infiltration in the tumor, and it is well-known that CD4 T cells can enhance antitumor activity of cytotoxic T lymphocytes." (PMID 37468850, 2023).
tumor (continued). "We found that the infiltrated tumor-killing immune cells in the higher-risk category were significantly lower, such as T cells CD8, T cells CD4 memory activated, and NK cells activated, which function as tumor suppressors in the progression of malignancy." (PMID 36890266, 2023). "CAR T cell–secretion of mIL-18 increased recruitment of tumor-specific CD4+ (on day 3) and especially CD8+ (on days 3 and 6) endogenous T cells." (PMID 36951942, 2023). "The recruitment, proliferation, and effector function of CD8 T-cell is enhanced by tumor-specific CD4 T-cells that reside within the TIME19." (PMID 37337080, 2023). "The goal of this project was to use recent developments in next generation sequencing (NGS) and TCR clonal analysis to develop a simple, easily standardized measure of anti-tumor CD4 and CD8 memory T-cell response." (PMID 37033929, 2023). "A previous study reported that tumor-infiltrating CD4+ T cells can upregulate some immune checkpoint genes, including PD-1, T-cell immunoglobulin, mucin domain-3, cytotoxic T lymphocyte associated protein-4, and lymphocyte-activation-gene-3." (PMID 37007145, 2023). "MDSC-derived IL-1β induces IL-17 secretion by CD4+ T cells leading to curtailed anti-tumor effect of 5-FU against several kinds of tumors including lymphoma, breast cancer, melanoma, and lung cancer." (PMID 36932407, 2023). "According to TCGA database, strong infiltration of CD8+ T cells, CD4+ T cells and regulatory T cells (FoxP3) is noticed in the tumor microenvironment of UM patients expressing high levels of VISTA." (PMID 37662962, 2023). "We have previously shown that a long H3K27M14–40 peptide vaccine, H3K27M-vac, induced CD4+ T cell-mediated immune responses in a major histocompatibility complex (MHC)-humanized mouse tumor model." (PMID 37735561, 2023). "In these melanomas, tumor infiltrating lymphocytes, including CD4+ T cells, CD8+ T cells, Tregs, and DCs, were found, but organized lymphoid structures in situ were not investigated." (PMID 38111571, 2023). "The tumour sections were stained with anti-human CD45 antibody, anti-human CD4 antibody, anti-human CD8α antibody, anti-human Foxp 3 antibody and the distribution of T cells in tumours was immunohistochemically investigated." (PMID 36166071, 2023). "Pinellia pedatisecta Schott extract (PE) promoted the expression of MHCII, CD80, CD86 and IL-12, the proliferation of CD4+ and CD8+ T cells, and induced the differentiation of IFN-y+CD4+ and GZMB+CD8+ T cells in tumor-associated dendritic cells (TADC)." (PMID 37355637, 2023). "The model also allows reliable measurement of the extent of vaccine-induced tumor growth inhibition together with the quantitative and qualitative monitoring of tumor-specific CD4+ and CD8+ T cell responses." (PMID 37626903, 2023). "Previously, it has been reported that pDCs can generate Tregs from naive CD4+ T cells, thereby contributing to tumor immune escape." (PMID 36982677, 2023). "Regarding this, BG showed a major early impact (day 2) on CD4+ T cells, which can play a coordinator role in cancer immunosurveillance, driving recruitment and anti-tumor programming of myeloid cells." (PMID 37816712, 2023). "This work provides a strong rationale to enhance tumor killing by boosting CD4 CTLs, especially in the setting of CD8 T-cell dysfunction and/or MHC-I downregulation." (PMID 37185301, 2023). "IL-2 and IFN-γ were upregulated in the tumor microenvironment in the combination treated group, as were CD4 + T lymphocytes." (PMID 37253929, 2023). "T regulatory immunocompetent cells can make up as much as 20–30% of the total CD3+CD4+ population around the TME, thus causing large numbers of tumour-infiltrating lymphocytes (TILs)." (PMID 36980527, 2023). "We generated condition-specific (i.e., CLR or DII) CNN models with the adequate classification accuracy when using B cells, CD4+ T cells, tumor cells, M2 macrophages, and granulocytes as anchor cell types across a range of k-NN sizes (10 ≤ k ≤ 50)." (PMID 37720335, 2023).